Y_RNA (Y RNA )
Gene: Miscellaneous RNA gene on chromosome 1 (110,764,408 to 110,764,506, reverse strand). Ensembl gene ENSG00000199710.
Homologues: Orthologues: chimpanzee Y_RNA (99% identical), macaque Y_RNA (88% identical), pig Y_RNA (76% identical). Paralogues in human: Y_RNA (92% identical), RNY3 (91% identical), Y_RNA (90% identical), RNY3P1 (89% identical), Y_RNA (89% identical), RNY3P2 (88% identical), Y_RNA (88% identical), RNY3P14 (87% identical), Y_RNA (87% identical), Y_RNA (86% identical), RNY3P13 (85% identical), RNY3P4 (85% identical), and 98 more.